SLAMF7 (SLAM family member 7)
Diseases named in the same sentence as SLAMF7 in open-access papers (continued):
Sharing a sentence is not in itself a finding about the gene and the disease.
melanoma (6 papers, 2017 to 2025). A malignant, usually aggressive tumor composed of atypical, neoplastic melanocytes. "Furthermore BTLA expression on CD8+ tumor-infiltrating lymphocytes was associated with improved clinical outcome in melanoma, aligning with our observation that SLAMF7 co-stimulation supports a less-differentiated, cytotoxic phenotype with sustained effector capacity." (PMID 40909279, 2025). "TCGA analysis has revealed an enrichment of SLAMF7 in melanoma and a correlation between SLAMF7 and favorable prognosis." (PMID 38476238, 2024). "In this regard it should be mentioned that both, the bladder cancer and melanoma study showed elevated expression of SLAMF7 on tumor antigen-specific CD4+ CTL and that targeting SLAMF7 with agonistic antibodies enhanced the cytotoxic activity of CD4+ T cells." (PMID 37965314, 2023). "SLAMF7 mRNA and protein levels are elevated in a subset of human melanoma tissues (data from The Cancer Genome Atlas and The Human Protein Atlas), making SLAMF7 an attractive immunotherapeutic target in for treating SLAMF7-positive melanoma patients." (PMID 28211524, 2017). "We validated the expression of DUSP1, SLAMF7 and EVI2B in human melanoma cell UACC62 and UACC257 after 8 Gy gamma-ray." (PMID 39687627, 2024). "The melanoma immunotherapy dataset PRJEB23709(n=91), GSE100797(n=25), GSE78220(n=28), GSE91061(n=109), Nathanson_2017(n=24), phs000452(n=153) were included to analyze the influence of DUSP1, CXCL13, SLAMF7 and EVI2B in immunotherapy response." (PMID 39687627, 2024). "According to the melanoma SCRS data, all mir-149 targets identified were expressed in lymphocytes, some of which were exclusively expressed in this cell type and include CD96, CD48, SLAMF7, FASLG, NUGGC and NLRC5." (PMID 32024530, 2020).
Sepsis (6 papers, 2022 to 2025). Sepsis is defined as life-threatening organ dysfunction caused by a dysregulated host response to infection. "Overall, our results showed that SLAMF7 expression on monocytes was elevated in sepsis patients and was associated with sepsis progress, suggesting a possible connection between SLAMF7 and sepsis." (PMID 36749634, 2023). "Data showed that LPS treatment and P. aeruginosa (a common pathogenic bacterium in sepsis) infection induced the expression of Slamf7 in both RAW264.7 cell lines in a time- and dose-dependent manner." (PMID 36749634, 2023). "Consistent with the data from the patients with sepsis, the percentage of SLAMF7+F4/80+ macrophages in the peritoneal lavage (PL) was significantly elevated in LPS-, P. aeruginosa–, or CLP-induced septic mice." (PMID 36749634, 2023). "Taken together, our findings reveal a negative regulatory role of SLAMF7 in polymicrobial sepsis, thus providing sights into the treatment of sepsis." (PMID 36749634, 2023). "We found that the expression of SLAMF7 on monocytes/macrophages was significantly elevated in patients with sepsis and in septic mice." (PMID 36749634, 2023). "In summary, this study provides evidence that SLAMF7 is an important negative regulator of sepsis-induced inflammation and reveals that SLAMF7 cooperates with SHIP1 to inhibit TRAF6 ubiquitination and suppress proinflammatory cytokine production." (PMID 36749634, 2023). "After antibiotic treatment, SLAMF7 expression in macrophages was decreased 10 days after CLP, consistent with downregulated expression of SLAMF7 in patients with sepsis after treatment." (PMID 36749634, 2023). "SLAMF7 expression was significantly elevated on peripheral monocytes of patients with sepsis and varied with the disease severity." (PMID 36749634, 2023). "To explored the role of SLAMF7 in the mouse model of sepsis-induced immunosuppression, we established a lethal CLP model with antibiotics in WT and SLAMF7-KO mice, followed by infection with P. aeruginosa 15 days later." (PMID 36749634, 2023). "Here, we identified an Ig-like receptor called signaling lymphocyte activation molecular family 7 (SLAMF7) as a key suppressor of inflammation during sepsis." (PMID 36749634, 2023). "SLAMF7 expression was elevated in both monocytes from patients with sepsis and macrophages from septic mice." (PMID 36749634, 2023). "Consistently, SLAMF7 KO in mice reduced their survival rate and aggravated sepsis by amplifying inflammation." (PMID 36749634, 2023). "To further confirm the involvement of SLAMF7 in sepsis progress, we activated SLAMF7 in vivo with rmSLAMF7 protein and observed the survival rates and lung histopathology of mice after sepsis induction." (PMID 36749634, 2023). "In this study, we observed upregulated expression of SLAMF7 in sepsis and demonstrated that SLAMF7 negatively regulated sepsis-induced inflammation." (PMID 36749634, 2023). "On the other hand, it was recently reported that SLAMF7 acts as a key suppressor of inflammation during sepsis." (PMID 37754488, 2023). "To demonstrate that SLAMF7 exerts its function in sepsis through macrophages, we depleted macrophages in WT and SLAMF7-KO septic mice through clodronate liposomes and then established a CLP model." (PMID 36749634, 2023). "Thus, we revealed the protective role of SLAMF7 in sepsis through its inhibition of the inflammatory response." (PMID 36749634, 2023). "Overall, this study demonstrated a negative regulatory role of SLAMF7 in sepsis-induced inflammation and revealed the signal transduction mechanism involved in this process, which may provide new sights into the therapeutic targets for sepsis." (PMID 36749634, 2023). "We thus evaluated the alternation of SLAMF7 expression in the progress of sepsis." (PMID 36749634, 2023).
Sepsis (continued). "Our study sheds light on the regulatory role of SLAMF7 in sepsis and uncovers the interaction between SLAMF7 and TRAF6/SHIP1 to transmit downstream signals, which may provide support for the development of therapeutic strategies for sepsis." (PMID 36749634, 2023). "Therefore, we concluded that SLAMF7 primarily exerted an antiinflammatory role in the early acute phase of sepsis, but had a limited effect on sepsis-induced immunosuppression, which merits further investigation." (PMID 36749634, 2023). "To explore whether SLAMF7 regulate the production of proinflammatory cytokines induced by sepsis in vivo, we determined the concentrations of TNF-α, IL-1β, and IL-6 in serum and supernatants of liver, lung, and PL." (PMID 36749634, 2023). "To investigate whether SLAMF7 is involved in the regulation stage of immunosuppression, we generated mouse models of sepsis immunosuppression according to previous studies." (PMID 36749634, 2023). "Finally, a rmSLAMF7 peptide agonist or genetic KO of SLAMF7 in mice demonstrated that SLAMF7 protected against lethal sepsis and endotoxemia by suppressing inflammatory responses." (PMID 36749634, 2023). "Furthermore, activation of SLAMF7 signal by recombined protein rescued mice from lethal sepsis, contributing to a better overall survival, while SLAMF7 KO accelerated sepsis by amplifying inflammatory responses." (PMID 36749634, 2023). "Finally, we demonstrated that SLAMF7 protected against lethal sepsis and endotoxemia by downregulating macrophage proinflammatory cytokines and suppressing inflammation-induced organ damage." (PMID 36749634, 2023). "KO of SLAMF7 contributes to the exacerbated inflammatory response in sepsis." (PMID 36749634, 2023). "Thus, we demonstrated that SLAMF7 attenuated the in vivo inflammatory response in sepsis." (PMID 36749634, 2023). "To fully reveal the in vivo function of SLAMF7 in the development of sepsis, we further established LPS, P. aeruginosa, and CLP sepsis mouse models with WT and SLAMF7-KO mice." (PMID 36749634, 2023). "Meanwhile, SLAMF7 expression was induced by TLR receptors and was tightly related to the progress of sepsis." (PMID 36749634, 2023). "We found that KO of SLAMF7 did not affect the survival rate of the mice with sepsis-induced immunosuppression." (PMID 36749634, 2023). "In this study, we demonstrated the negative modulatory role of SLAMF7 in the inflammatory response during sepsis." (PMID 36749634, 2023). "We collected a series of blood samples from patients with sepsis on their ICU admission day (day 0; patients were diagnosed with sepsis and admitted to the ICU on the same day) and 1, 3, 5, and 7 days after treatment to detect the expression of SLAMF7." (PMID 36749634, 2023). "To investigate the role of SLAMF7 in sepsis in vivo, we established sepsis mouse models in C57BL/6 mice by LPS injection (endotoxemia model), P. aeruginosa infection (bacterial sepsis model), or cecal ligation and puncture (CLP) (polymicrobial sepsis model)." (PMID 36749634, 2023). "Interestingly, data showed that the percentage of SLAMF7+ monocytes was strongly correlated with serum concentrations of C-reactive protein (CRP) (r = 0.38), which is a commonly used marker for inflammation and disease progress in sepsis." (PMID 36749634, 2023). "In summary, our results uncover the negative role of SLAMF7 in sepsis and inflammation, which may provide therapeutic strategies for sepsis treatment." (PMID 36749634, 2023). "Moreover, SLAMF7 did not affect the bacterial burden in vivo, which mostly contributed to mortality of the mice with sepsis-induced immunosuppression." (PMID 36749634, 2023). "The results showed that the expression of SLAMF7 in CD11b+CD14+ monocytes, but not CD3+ T cells, was significantly increased in patients with sepsis (n = 83) compared with expression levels in healthy donors (n = 81)." (PMID 36749634, 2023).
viral infection (6 papers, 2014 to 2025). "This study suggests that excessive SLAMF7 signaling between NK cells and SLAMF7 expressing cells in their microenvironment can cause pathological inflammation, highlighting the importance of SLAMF7–SLAMF7 interactions between various immune cells during viral infection." (PMID 31744090, 2019). "While no studies have yet described a direct interaction between any particular virus and SLAMF7, there are numerous reports describing immuno-modulatory roles for SLAMF7 in the setting of viral infections." (PMID 31744090, 2019). "Compared to cluster 4, cluster 2 cells showed higher expression of SLAMF7, ZEB2, GZMB, GPR18, CD72, PDCD1 (PD1) and CRTAM that are known to be expressed in terminally differentiated effector cells in viral infections and various cancers." (PMID 38501302, 2024).
breast carcinoma (4 papers, 2023 to 2025). "Interestingly, another study suggested that SLAMF7 can express highly on solid breast cancer, and high SLAMF7 expression is associated with poor clinical outcomes, for which SLAMF7 mediates “don’t eat me” signals." (PMID 40835598, 2025). "The results showed that IGLL1, SLAMF7, SLAMF1, CD48, and LRRC8A were closely associated with immune infiltration in breast cancer (p < 0.05)." (PMID 38388382, 2024). "SLAMF7/CD319 mRNA expression was found to be enriched in breast cancer TCGA analysis, as compared to healthy breast tissue." (PMID 38476238, 2024). "On the other hand, CD48, SLAMF1, and SLAMF7 were highly expressed in HER2 + and triple-negative breast cancer (TNBC), and IGLL1 was highly expressed in ER + and TNBC tissues; These six key genes are closely associated with immune infiltration in breast cancer." (PMID 38388382, 2024). "We evaluated the correlation between the expression of IGLL1, SLAMF7, SLAMF1, CD48, and LRRC8A and the immune infiltration profile in breast cancer using data downloaded from TCGA." (PMID 38388382, 2024). "A total of 88 candidate genes related to breast cancer prognosis were screened, of which CD48, SLAMF7, SLAMF1, IGLL1, IGHA1, and LRRC8A were key genes." (PMID 38388382, 2024). "In three different types of breast cancer cells, differential expression was also observed in genes including HERV-K_1q23.3, CD48, SLAMF1, SLAMF7, HERV-K_22q11.23, IGLL1, HERV-K_9q34.11, and LRRC8A." (PMID 38388382, 2024). "In breast cancer, the high expression of SLAMF1, SLAMF7, CD48, and IGLL1 is positively correlated with the infiltration of B cells, CD8 + T cells, CD4 + T cells, macrophages, neutrophils, and dendritic cells." (PMID 38388382, 2024). "SLAMF7 was included in the immune gene signatures to predict TNBC NAC response, and it was also used as a target by a nanoconjugate system to activate an immune response for breast cancer." (PMID 37190123, 2023). "Further research is needed to investigate these results, and the results of the drug sensitivity analysis indicated that IGLL1, SLAMF7, SLAMF1, CD48, and LRRC8A might decrease sensitivity to specific chemotherapy drugs, further affecting the treatment efficacy for breast cancer." (PMID 38388382, 2024).
COVID-19 (4 papers, 2023 to 2025). A disease caused by infection with severe acute respiratory syndrome coronavirus 2. "In addition to activation of plasma-related pathways, we also observed in naïve B cells that FCER2 was downregulated while SLAMF7 was upregulated suggesting significant activation of these cells in COVID-19." (PMID 37848421, 2023). "Plasmablasts from patients with COVID-19 expressed higher levels of XBP1 and SLAMF7 than plasmablasts from HIV-1+ patients, suggesting greater maturation." (PMID 36992700, 2023). "In addition, IFI30 was specifically upregulated in monocytes during HIV-1 infection, whereas SLAMF7 and IFIT3 were upregulated in plasmablasts and T cells from COVID-19 patients respectively." (PMID 36992700, 2023).
atherosclerosis (3 papers, 2018 to 2025). A disease characterized by the build-up of fatty material and calcium deposition in the arterial wall resulting in partial or complete occlusion of the arterial lumen. "SLAMF7 is also upregulated in monocytes/macrophages in several types of viral chronic inflammation as well as in myelofibrosis and atherosclerosis." (PMID 40231463, 2025). "Methylation of SLAMF7 has also been identified as a regulator in atherosclerosis." (PMID 33593402, 2021).
Autoimmunity (3 papers, 2021 to 2025). The occurrence of an immune reaction against the organism's own cells or tissues. "Here we have shown, using multiple murine models of MS, that the immune cell receptor SLAMF7 regulates susceptibility to CNS autoimmunity through B cells and memory T cell responses." (PMID 36199066, 2022). "The association between SLAMF7 expression/signaling in B cells and susceptibility to CNS autoimmunity is supported by our adoptive transfer studies and is particularly exciting considering how the new B cell-depleting therapies are changing the landscape of contemporary MS treatment." (PMID 36199066, 2022). "SLAMF7/CD319 (mouse CRACC) has also been implicated in autoimmunity, although with mixed findings." (PMID 33936082, 2021). "In support of this, and relevant to our studies here showing a role for SLAMF7 expression on B cells in the setting of neuro-autoimmunity, a recent study has shown that SLAMF7 signaling on B cells is inhibitory and antagonizes BCR activation." (PMID 36199066, 2022). "While our above studies identified a functional role for SLAMF7 in the regulation of CNS autoimmunity in mice, the importance of SLAMF7 in the human CNS immune landscape, particularly as it relates to MS, remains undefined." (PMID 36199066, 2022). "We found that μMT mice reconstituted with SLAMF7−/− B cells experienced significantly increased incidence of EAE symptoms compared to mice reconstituted with WT B cells, confirming an intrinsic role for SLAMF7 expression in B cells as responsible for regulating CNS autoimmunity." (PMID 36199066, 2022). "Given the consequences of elevated type I IFN secretion in various disorders, the involvement of SLAMF7 and SLAMF8 extends beyond infectious diseases to cancer and autoimmunity." (PMID 40231463, 2025).
chronic lymphocytic leukemia (3 papers, 2018 to 2026). "A recent analysis of gene expression data in hematopoietic malignancies confirmed high SLAMF7 expression on myeloma tumors, but also identified high SLAMF7 expression on tumors in patients with myelodysplastic syndrome, chronic lymphocytic leukemia, and diffuse large B cell lymphoma." (PMID 30455698, 2018). "In addition, expression of SLAMF7 has also been identified on tumor cells in a subset of patients with chronic lymphocytic leukemia, myelodysplastic syndrome, diffuse large B cell lymphoma, and peripheral T cell lymphoma." (PMID 30455698, 2018). "SLAMF7, also known as CD319, a SLAM (signaling lymphocytic activation molecule) family receptor, is relatively weakly expressed on chronic lymphocytic leukemia (CLL) B cells." (PMID 41683508, 2026).
diffuse large B-cell lymphoma (3 papers, 2018 to 2025). "Moreover, SLAMF7 also does not impact on phagocytosis induction by CD20 antibody rituximab nor associates with overall survival of Diffuse Large B-Cell Lymphoma patients." (PMID 30710089, 2019). "As such, diffuse large B-cell lymphoma (DLBCL), the most common subtype of non-Hodgkin’s lymphoma (NHL), was identified as a suitable target for CD47 blocking therapy based on its high SLAMF7 mRNA levels." (PMID 30710089, 2019).
HIV-1 infection (3 papers, 2019 to 2023). The type species of lentivirus and the etiologic agent of acquired immunodeficiency syndrome (AIDS). "More in-depth analyses revealed that CD16+ monocytes were responsible for this increase in SLAMF7+ cells which fits with previous studies showing CD16+ monocytes are increased in chronic HIV-1 infection." (PMID 31744090, 2019). "We also found that SLAMF7 signaling in human monocytes inhibits the production of various alpha chemokines, but not host restriction factors that are critical for combatting HIV-1 infection at the cellular level." (PMID 31744090, 2019). "Our group has recently identified SLAMF7 as playing an important role in the modulation of peripheral immune activation in chronic HIV-1 infection." (PMID 31744090, 2019). "In addition, chronic HIV-1 infection increases SLAMF7 expression, whereas SLAMF7 negatively regulates IFN-α–mediated CXCL10 production to inhibit the induction of inflammatory monocyte subsets." (PMID 36749634, 2023). "Finally, in vitro HIV-1 infection studies revealed that SLAMF7 activation on monocytes could robustly prevent their infection with HIV-1 through a CCR5/CCL3L1 mechanism." (PMID 31744090, 2019). "As chronic HIV-1 infection is known to up-regulate SLAMF7 on monocytes and T cells, it is interesting to hypothesize how this affects other SLAMF7 expressing immune cells which regularly interact with monocytes, and what effect this would have on chronic inflammation in HIV infection." (PMID 31744090, 2019).
liver cancer (3 papers, 2024 to 2025). An epithelial or non-epithelial malignant neoplasm that arises from the liver. "Analysis of LIHC data from TCGA further showed the functional relationship between TM4SF5 and SLAMF7 in liver cancer." (PMID 39828766, 2025).
lymphoma (3 papers, 2022 to 2025). A malignant (clonal) proliferation of B- lymphocytes or T- lymphocytes which involves the lymph nodes, bone marrow and/or extranodal sites. "Furthermore, we chose two SLAMF7-expressing tumor cells, a human lymphoma cell line Raji and a human hepatocarcinoma cell line MHCC97H, sorted on SLAMF7 expression respectively and cocultured with hDNT." (PMID 41168829, 2025). "IHC also detected SLAMF7+ cells in ET‐P2 mouse spleen, which contained numerous CD3+ lymphoma cells and lacked B cells by CD20 and EBER‐ISH staining." (PMID 39877932, 2025).
ovarian carcinoma (3 papers, 2020 to 2023). A malignant neoplasm originating from the surface ovarian epithelium. "On the other hand, in some other types of cancer, such as ovarian cancer and RCC, low expression of SLAMF7 has been associated with poor prognosis, suggesting that SLAMF7 may play a role in suppressing tumor growth in these contexts." (PMID 37251372, 2023).
asthma (2 papers, 2020 to 2023). "The Venn diagram showed that there are indeed common DEGs between obesity and asthma, namely IL36RN, PHACTR3, SLAMF7, AKR1B10 and RNF182." (PMID 37723557, 2023).